TNF (tumor necrosis factor)
Diseases named in the same sentence as TNF in open-access papers (continued):
Sharing a sentence is not in itself a finding about the gene and the disease.
tumor (continued). "Moreover, tumor-derived TNF-α activates NF-κB pathway in mast cells, causing mast cells to express PD-L1." (PMID 34692696, 2021). "Pro-inflammatory cytokines (IL-6, IL-8, TNF-α, soluble interleukin-2 receptor (sIL-2R)) are key-molecules involved in the crosstalk between stromal and cancer cells, their expression being, to some extent, associated with tumor growth promotion or inhibition." (PMID 34202728, 2021). "Moreover, the observation that tumor-associated macrophages in irradiated tissue have enhanced secretion of pro-inflammatory cytokines IL-6, IL-12, TNF-α, and IFNγ further supports our results." (PMID 34298925, 2021). "Additionally, neutrophils were shown to cause tumor cell death via TNF-α expression that led to localized acute ischemia due to perfusion loss." (PMID 34563270, 2021). "Moreover, estrogenic influence, pro-inflammatory adipokines such as tumor necrosis factor-alpha (TNFα), and leptin are also reported to be tumor-associated biochemical risk factors." (PMID 34940056, 2021). "TNFα was identified in 1975 as a molecule capable of causing tumor necrosis at high concentration." (PMID 33540543, 2021). "Thus, oral administration of A. shahii to microbiota-depleted mice reconstituted the ability of tumour-associated myeloid cells to produce TNF leading to an anti-tumour response." (PMID 34658896, 2021). "TNF-α is produced by macrophages and can act on vascular endothelial cells, causing damage to endothelial cells and vascular inflammation, resulting in changes in vascular function and the development and metastasis of tumor cells." (PMID 34899952, 2021). "Interestingly, four sequential systemic dosings with naked TNF-armed MYXV caused comparable anti-tumor efficacy to a single systemic dosing of vMyx-hTNF/PBMCs." (PMID 34553039, 2021). "Similarly, the last effectors can deliver Th1 cytokines that reprogramme tumour-associated M2 macrophages, which discharge arginase and inducible nitric oxide synthase, into M1 killer cells that produce IL-12 and TNFα." (PMID 34336101, 2021). "Paracrine interactions between tumor cells and cancer-associated fibroblasts promote the release of TNF-α, which induces tumor-cell apoptosis, activates the endothelium and granulocytes regulating the immune cells and remodels the microenvironment and promote invasion and metastasis." (PMID 34830880, 2021). "To assess which factors present in the conditioned medium may regulate GITRL expression, we determined release of a panel of tumor-associated cytokines, namely TGFβ, IFNγ, IL-10, TNF and IL-2." (PMID 33538861, 2021). "TNF-α activates tumor-associated macrophages to present antitumoral effects." (PMID 33411055, 2021). "However, TNF-α has been implicated in angiogenesis during inflammation, wound repair, and tumor growth." (PMID 34445558, 2021). "Deficiency of TNF promoted tumor progression whereas conversely, a monocyte/macrophage-specific deficiency in HO-1 or inhibition of HO-1 reversed the immunosuppressive effect of macrophages, and reduced tumor progression post-I/R." (PMID 33671004, 2021). "TNF-mediated signaling on tumor cells was also implicated in the process." (PMID 33917839, 2021). "We have also identified prostasin as a regulator of cytokine and reactive oxygen species production including IFNγ, tumor necrosis factor α (TNF-α) and the inducible nitric oxide synthase (iNOS), all of which are implicated for a role in the tumor microenvironment and progression." (PMID 34240739, 2021). "Based on the GSEA outcomes, we hypothesised that the tumour EC apoptosis might be caused by TNFα produced due to STING activation, since TNFα exerts a potent anti-tumour effect derived from tumour vascular destruction." (PMID 34285232, 2021). "In tumor microenvironment, the tumor-associated macrophages could secret the TNFα, and induce tumor necrosis through the activation of caspase-8, the translocation of PD-L1, and the cleavage of GSDMC." (PMID 34421915, 2021).
tumor (continued). "Inflammatory ILs and TNF-α have been hypothesized to serve as prospective tumor markers and have been associated with increased tumor invasion and angiogenesis through their ability to inhibit HIF expression." (PMID 34452568, 2021). "Notably, no significant haemorrhage occurred in the liver, kidney, and spleen because Vadimezan specifically targets tumour endothelial cells and induces tumour necrosis factor-α (TNF-α) secretion, which is known to cause haemorrhagic necrosis in tumours." (PMID 33986264, 2021). "Genetic loss of TNF and its death-signaling molecules (e.g., Tnfr1 and Casp8) led to uncontrolled tumor growth, whereas loss of molecules involved in ubiquitinating RIPK1 (e.g., Traf2 and Birc2/3) resulted in tumor rejection following immune checkpoint blockade." (PMID 34752416, 2021). "TNF-α was overexpressed in high-grade ccRCC tissues and tumor-associated macrophages." (PMID 33920158, 2021). "A variety of cytokines, chemokines can also destabilize these junctions and inflammatory mediators frequently expressed by cancer cells and tumor-associated cells, including interleukin-1β (IL-1β), TNF-α, interferon-γ (IFN-γ), CCL2, and CXCL8 (reviewed in 104)." (PMID 33442395, 2021). "However, since Smac mimetics cause innate immune cells to release TNF, tumor infiltrating lymphocytes are believed to aid in reducing tumor volume." (PMID 33546280, 2021). "TNF-α, IL-6 and IL-17 have known roles in tumor growth and promotion; IL-6 and IL-10 are produced by tumor-associated macrophages and create conditions of immune suppression and angiogenesis; IL-1β and IL-6 promote angiogenesis and tumor invasion." (PMID 33396710, 2020). "Tumor necrosis factor-alpha (TNF-α) is known to be linked with tumor." (PMID 35095226, 2020). "Several studies have demonstrated that tumor necrosis triggers inflammation, which facilitates the influx of lymphocytes and the upregulation of PD-L1, related to tumor necrosis factor-α, and that necrosis or inflammation was closely linked to tumor recurrence and worse survival." (PMID 32156047, 2020). "In addition, rutin downregulated the expression of VEGF, IL-1β and enhanced the expression of TNF-α in tumor associated macrophage." (PMID 32823876, 2020). "TNF is a cytokine secreted by macrophages that can directly cause death of tumor cells." (PMID 32775426, 2020). "Several publications have appeared in recent years documenting the increased expression of interleukin 8 (CXCL8, IL-8), interleukin 6 (IL-6), tumor necrosis factor (TNFα) in cancer cells, infiltrating neutrophils, endothelial cells and tumor-associated macrophages." (PMID 33266223, 2020). "In a murine model of spontaneous insulinoma, low‐dose irradiation (2 Gy) in late‐stage tumor Rip‐Tag5 mice induced M1 TAM‐associated cytokines (e.g. TNF‐α, IL‐12p70 and IFN‐γ), and suppressed p38 mitogen‐activated protein (p38MAPK), leading to the acquisition of M1 macrophage phenotype." (PMID 32994997, 2020). "Whilst the independent influence of oncogene-dependent inflammation is yet to be determined in this model, a combination of β-catenin expression and high fat diet induced a strong tumour-promoting inflammatory response, which was associated with TNFα positive macrophages." (PMID 32325966, 2020). "For example, to overcome the barrier of systemically safe, tumor specific TNF delivery, Yuan and colleagues developed a novel system whereby systemic delivery of Adeno-Associated Virus bacterioPhage-TNF (AAVP-TNF) enables tumor vasculature-targeted gene therapy." (PMID 32053868, 2020). "Additionally, priming of tumor-associated neutrophils with IFNγ and TNF contributed to alterations in the polarization of neutrophils rendering them from tumor promoters to tumor suppressors." (PMID 33363012, 2020). "Notably, upon TLR triggering, positive correlations between IFNλ1‐producing cDC1s and IFNα/TNFα‐producing pDCs appeared within tumor microenvironment and were both linked likewise with clinical outcome." (PMID 33282290, 2020).
tumor (continued). "Similarly, in the AT3 model, NAM treatment was associated with increased tumor infiltration by CD4+ T cells expressing TNF alone, TNF and IFNG, as well as TNF, IFNG, and IL2." (PMID 32732875, 2020). "TNF-α is a cytokine capable of promoting tumor growth and migration, as high levels in the peripheral blood of cancer patients are associated with more advanced tumor stages and lymph node metastases." (PMID 33126617, 2020). "In murine models of human ovarian carcinoma or murine sarcoma, SM administration was associated with a rapid inflammatory burst of TNF and interferon-gamma (IFNγ), due to the reversion of tumour-associated macrophages from a pro-tumoural M2 phenotype to a pro-inflammatory MI-like phenotype." (PMID 31947615, 2020). "Furthermore, tumor-associated macrophages (TAMs) participate in CRC metastasization through the TNF-α mediated secretion of IL6, which was also found to directly promote the accumulation of MDSCs in tumors." (PMID 32722560, 2020). "Tumor-associated macrophages are a major source of IL-6 and TNFα in CRC." (PMID 32317968, 2020). "Moreover, in HCC (BNL and Hepa 1–6) tumor models, we showed that entolimod prevented mouse mortality caused by TNF combined with D-galactosamine (D-GalN) sensitization but did not diminish tumor growth suppression." (PMID 32027657, 2020). "Meanwhile, the authors found that TNF blockade could further enhance the infiltration of tumor-specific CD8+ T cells into the tumor microenvironment and draining lymph nodes caused by anti–PD-1 and anti–CTLA-4 monoclonal antibody combination therapy." (PMID 32226426, 2020). "Recently, we eported that PAMs could also inhibit the tumor growth of cancers by downregulating the expressions of inflammation and vascular growth associated with TNF-α and VEGF." (PMID 32799864, 2020). "Tumor associated macrophages in the resting phase secrete immune-suppressive cytokine IL-10, while during activation by lipopolysaccharide (LPS), they secrete proinflammatory cytokines IL-1β, IL-6 and TNF." (PMID 32120819, 2020). "Furthermore, they showed that when mice that were pre-treated with antibiotic and gavaged with A. shahii, the tumor-associated myeloid cells function to produce TNF was restored." (PMID 32582143, 2020). "Specifically, TNF has been implicated in immune cell migration into the tumor." (PMID 32523651, 2020). "In vitro neutralizing tumor necrosis factor α (TNFα) could inhibit the tumor progression caused by M2b culture medium and tumor IDO1 expression." (PMID 33214550, 2020). "In addition, the tumor-derived cytokines CXCL1, CCL3, CXCL2, TIMP-1, and TNF-α, which have been implicated in the generation, migration, and activation of MDSCs at the tumor site, were regulated by the modulation of MDSCs." (PMID 33091036, 2020). "Once within TME, the presence of type-1 IFNs shapes their phenotype towards an anti-tumor N1 polarization state, associated with increased tumor cytotoxicity, high neutrophil extracellular traps (NETs) expression, and enhanced TNFα and reactive oxygen intermediates expression." (PMID 32397392, 2020). "It is well-known that tumor cell necrosis could be caused by TNF activation of NF-κB accompanied with tissue damage or inflammation." (PMID 32117702, 2020). "Tissue necrosis factor-α (TNF-α) is an inflammatory cytokine released by macrophages, mast cells and T-lymphocytes and it is also implicated in tumor progression, cell survival, differentiation, invasion, metastases as well as secretion of cytokines and pro-angiogenic factors." (PMID 31690961, 2020). "After analyzing the association of TNF-α (rs1800629) SNP genotypes with other variables such as gender, age, tumor location and morphological pattern, our results suggested a statistically significant relationship only between the genotypes and the morphological pattern (p = 0.032)." (PMID 31983162, 2020).
tumor (continued). "The group of proinflammatory cytokines also revealed a reduced expression of TNF-α, which may result from an increased pro-angiogenic activity of tumor cells caused by negative regulation by VEGF." (PMID 32488850, 2020). "Tumor-associated macrophages (TAMs) are a major source of IL-6 and TNFα in CRC." (PMID 32317968, 2020). "IL-10 is secreted in the TME and it has been shown to induce an exhausted phenotype on tumor infiltrating T cells characterized by low proliferation and suppressed secretion of cytokines associated with an effector phenotype as IL-2, IFNγ and TNFα." (PMID 32937953, 2020). "Additionally, MCPyV TAg-specific cells gated on CD3+CD4+TNFα+ cells were polyfunctional for IL-2 and the Th1 effector molecules granzyme B, IFNγ, and TNFα, a feature associated with immune-mediated tumor clearance." (PMID 33362774, 2020). "In this context, tumor immune escape can be caused by a loss of sensitivity to TNF." (PMID 33344447, 2020). "In addition to the IFN-γ signaling pathway, the loss of sensitivity to tumor necrosis factor (TNF) has been demonstrated to promote tumor immune escape through the upregulation of anti-apoptotic proteins, such as BCL-2." (PMID 32083005, 2020). "Hypoxia in the tumor microenvironment causes tumor cells to secrete chemokines, such as interleukin-1 (IL-1), tumor necrosis factor alpha (TNF-alpha), or interleukin 8 (IL-8), which activates neutrophils to produce more pro-oncogenetic and immunosuppressive factors." (PMID 32719600, 2020). "Then, we likely suggested that on 21st day, the tumour-bearing group (21 W) was subjected to more intense effects of the inflammatory process, higher interleukin IL-4 are associated with increased levels of IL-6, TNF and INF in the W group." (PMID 30975087, 2019). "Interestingly, TNFα has initially been described as a factor released by host cells to induce tumour necrosis, therefore a role for TNFα to regulate tumour development and growth was implicated." (PMID 30995806, 2019). "Also, Ang-2 and hypoxia cause TEM influx into the tumor microenvironment, and the TEMs mediate downregulation of TNF-α supporting cancer cell survival and causing metastasis of the primary tumor." (PMID 31474975, 2019). "However, little is known about the association of Pgp and TNF-α, and their impact on tumor phenotype." (PMID 31137684, 2019). "In different types of cancer, multiple lines of evidence have supported that inflammatory cytokines secreted by tumor-associated macrophages (which can represent half of the tumor mass), including tumor necrosis factor alpha (TNF-α), are capable of inducing EMT events in cancer cells." (PMID 31788442, 2019). "Moreover, Nfkb2 was shown to be frequently mutated in cancers and aberrant TNF signaling has been implicated in neoplastic diseases." (PMID 31134075, 2019). "Tumor-associated macrophages (TAMs) are subdivided into two subsets, M1 and M2 macrophages, based on their capacity to express or produce Nitric Oxide Synthase/IL-12/TNF-α or arginase-1/IL-10/TGF-β, respectively." (PMID 31480382, 2019). "Although TNF-α causes necrosis of some types of tumors, it might act as an inducer of tissue remodeling required for tumor growth and spread." (PMID 31516665, 2019). "This is associated with increased TNF levels and increased number of tumor associated macrophages." (PMID 32232096, 2019). "Increases in PD-L1 expression can occur on SCC cells as a result of mutations in tumor cell signaling pathways or exposure of tumor cells to inflammatory cytokines IL-1, IL-6, GM-CSF, IFNγ, TNFα, and VEGF and the gamma-chain cytokines IL-2, IL-7, IL-10, IL-15, and IL-21." (PMID 31554151, 2019). "Suppressive role of tumor-derived TNFα and TGFβ on pDCs have been implicated in a previous study." (PMID 31440253, 2019). "Altogether, preoperative serum IL-8 and TNF-α levels may serve as predictors for the tumor recurrence risk of HCC patients." (PMID 31781194, 2019).
tumor (continued). "TNF-α is one of the tumor-associated cytokines with angiogenesis properties." (PMID 30862840, 2019). "In addition, Cygb-deficient mice show elevated TNF-α and IL-6 in tumor and non-tumor tissue of the liver and lung." (PMID 31920538, 2019). "The sensitizing effect of MLN4924 for TNF-induced cell death might also affect cells of the tumor microenvironment, e.g., tumor associated T cells and/or myeloid cells." (PMID 31406107, 2019). "Therefore, we next measured the production of the effector cytokines IFNγ and TNFα by tumor-associated CD8+ and CD4+ T cells in our involution group tumors." (PMID 31244852, 2019). "In addition, NKp44-mediated recognition of tumor associated fibroblasts can lead to the release of high amounts of TNF-α, thus influencing the vascular permeability and inducing pro-inflammatory responses in the tumor microenvironment." (PMID 31024551, 2019). "Elevated levels of TNF-α have been associated with increased levels of infiltrating immature myeloid cells which develop into pro-tumorigenic cells such as tumor associated macrophages and neutrophils (TAMs and TANs) once they are exposed to the tumor microenvironment." (PMID 30894857, 2019). "Pleiotropic cytokine TNFα is associated with tumor cell growth, invasion, and metastasis." (PMID 31311202, 2019). "Conversely, our data suggest that modulation of TNFα or cGAS/STING signaling may allow survival of BRCA-deficient tumor cells, and warrants care in using TNFα antagonists in BRCA mutation carriers." (PMID 30626869, 2019). "In addition, DAB-Lf dendriplex encoding TNFα had the same therapeutic outcome as DAB-Tf dendriplex on DU145 tumors (50% tumor suppression)." (PMID 29493296, 2018). "Moreover, TNFα targets tumor-associated vasculature by elimination of vascular lining and induction of hyper-permeability within tumor environment." (PMID 29588627, 2018). "The mechanism underlying TNFα pro-tumor activity was nicely described in ovarian cancer." (PMID 30154786, 2018). "In addition, tumor necrosis factor-α is secreted by tumor-associated macrophages and is known to induce cellular oxidative stress." (PMID 29770168, 2018). "In the tumor microenvironment, TNFα is produced by tumor cells and tumor-associated stromal cells and plays crucial roles in the expression of a variety of inflammatory cytokines and the regulation of tumor invasion and metastasis." (PMID 30177620, 2018). "In addition, TNF-α is able to act on the tumor-associated vasculature by inducing hyperpermeability and destruction of the vascular lining." (PMID 29493296, 2018). "High doses of TNF-α can inhibit tumor angiogenesis and induce apoptosis, but long-term treatment with low doses causes proliferation, invasion, angiogenesis and metastasis of tumor cells." (PMID 29467927, 2018). "In this study we developed a novel, modular platform utilizing human IgG1 for generation of multivalent single-chain derivatives of the apoptosis-inducing TNF homology domain of TRAIL in combination with targeting of tumour-associated antigens, here demonstrated for EGFR." (PMID 29773864, 2018). "Although TNFα was first identified as an agent capable of causing tumor necrosis and was later considered an apoptotic inducer, new evidence suggests that TNFα induces a special form of cell death termed necroptosis that is programmed, but immunogenic, and thus suitable for in situ vaccination." (PMID 29468364, 2018). "Thus, understanding the mechanism underlying the resistance of tumours to TNF‐α toxicity and finding ways to overcome this resistance are urgently needed." (PMID 29632814, 2018). "Only for TNF-α, a significant positive association between expression in tumor tissue and MD among postmenopausal women was detected, but this may be a false positive result due to multiple testing." (PMID 30497427, 2018). "In addition, VEGF and TNF-α molecules are critical for the proliferation, angiogenesis, macrophage recruitment, and metastasis associated with tumor progression." (PMID 30034291, 2018).